TXN (thioredoxin)
Diseases named in the same sentence as TXN in open-access papers (continued):
Sharing a sentence is not in itself a finding about the gene and the disease.
cancer (continued). "Therefore, inhibiting the function of TXN and TXNRD disrupts the redox balance in cancer cells, leading to heightened oxidative stress and subsequent cell death." (PMID 39090114, 2024). "Small molecule inhibitors of the thioredoxin system have shown significant tumor-suppressing effects, suggesting that TXN may be a potential therapeutic target in cancer treatment." (PMID 36776308, 2023). "PML, C3, TXN, KRT6C, F2, PTK2, TNF, which could enable HIF-mediated inflammatory response during cancer development." (PMID 36845724, 2023). "Early approaches aimed to promote antioxidant activity for anti-cancer effect targeted antioxidants and ROS-scavenging systems, such as superoxide dismutase (SOD), glutathione peroxidases, peroxidoxins, glutaredoxin, thioredoxin, catalase, and nuclear factor erythroid 2-related factor 2 (Nrf2)." (PMID 33707480, 2021). "As suggested by the literature, the inhibition of the thioredoxin reductase–thioredoxin redox system by gold(I) and gold(III) complexes (e.g., auranofin and AuL12) and the subsequent production of ROS are able to trigger cancer cell apoptosis through mitochondrial impairment." (PMID 34440075, 2021). "In the case of CA1, T1-weighted phantom images of cancer cells (MCF-7, A549) could be generated based on the expression of thioredoxin." (PMID 33916181, 2021). "The thioredoxin (Trx) system, comprised of Trx, thioredoxin reductase (TrxR), and NADPH, is an antioxidant system previously identified as a target for therapies aimed at overcoming drug resistance in other cancers." (PMID 32138149, 2020). "In an effort to oppose the effects of ROS, cancer cells induce the expression of different antioxidant enzymes, including glutamate cysteine ligase (GCL), glutathione S-transferase (GST), glutathione peroxidase (GPX), SOD, CAT, and thioredoxin (Trx)." (PMID 32365852, 2020). "Therefore, cancer cells generally up-regulate multiple antioxidant systems including GSH and thioredoxin, buffering ROS levels to allow tumor cell progression." (PMID 29971019, 2018). "Importantly, the differences in the energetic requirements and kinetics of the PRDX/TXN/TXNRD, GPX/GSH/GSR, and catalase systems become particularly important if cancer treatments are targeting ROS metabolism by inhibiting NADPH production." (PMID 28744456, 2017). "TXN binds to and inhibits pro-apoptotic proteins, including apoptosis signal regulating kinase-1 (Ask-1) and tumor suppressor PTEN, a protein that attenuates the PI3K/Akt cell survival pathway when it is present in cancer cells." (PMID 26325518, 2015). "The observations that lung, non-small cell adenocarcinomas have highly enriched levels of TXN and PRDX1, suggest that these two components provide major antioxidant support in combating the oxidative stress accompanying this specific carcinoma in lung." (PMID 26569310, 2015). "Finally, the activity of several anti-cancer agents, such as suberoylanilide hydroxamic acid (SAHA) and curcumin, are thought to work in part by modulating this pathway, inhibiting thioredoxin and thioredoxin reductase, respectively." (PMID 19956548, 2009). "The inhibitory effect of RARA could be reversed by overexpression of TXN and PPM1F in both in vivo and in vitro experiments, further highlighting the vital role of inhibiting RARA in the treatment of inducing ferroptosis in cancer." (PMID 38902322, 2024). "Another example is given by the thioredoxin system (Trx), including NADPH, thioredoxin, and thioredoxin reductase, which plays a key role in redox homeostasis in all living cells, yet Trx-1 is overexpressed in many cancers and in DLBCL, conferring an advantage to lymphoma cells." (PMID 37759977, 2023). "A study showed that chemical TXN inhibitor induced ferroptosis in cancer cells, suggesting that the TXN system may act as a negative regulator of ferroptosis in cells." (PMID 38075884, 2023).
cancer (continued). "Importantly, the expression of gene sets identified behind the DAC and paracetamol interaction (namely, suppression of DAC-activated COX-2-PGE2 pathway, depletion of the GSH stores and thioredoxin response) significantly affects survival in HNSCC and other cancers in TCGA data sets." (PMID 33359448, 2021). "Additionally, thioredoxin activates ribonucleotide reductase, inhibits apoptosis signal regulating kinase 1, and induces HIF-1 and vascular endothelial growth factor (VEGF), contributing to cancer traits such as increased proliferation, inhibited apoptosis, and angiogenesis." (PMID 41333220, 2025). "In this regard, PRDX6, MAGOHB, NUCKS1, DCAF13, and TXN displayed an overall negative correlation with multiple immune checkpoints in LUAD, LUSC, and other cancer types." (PMID 37835514, 2023).
tumor (117 papers, 2005 to 2026). "The shift of TXNIP/TXN balance towards overexpression of TXNIP is associated with proliferation of endothelial cells during tumor angiogenesis." (PMID 34433833, 2021). "It is known that upregulated thioredoxin and glutaredoxin can be a cause of chemotherapy resistance in various tumour entities." (PMID 33750814, 2021). "Thioredoxin is a thiol oxidoreductase that is ubiquitously expressed and is highly expressed in a variety of malignancies and associated with aggressive tumor growth and poor survival." (PMID 32923383, 2020). "TXNIP has been implicated as both a tumor suppressor and an oncogene and is critical for regulating the redox status in cells through its interaction with thioredoxin (TRX)." (PMID 30479697, 2018). "Thioredoxin (Trx) overexpression is known to be a cause of chemotherapy resistance in various tumor entities." (PMID 30248944, 2018). "TXNRD1 associated with aggressive tumor growth and poor survival rate plays an important role in regulation of TXN." (PMID 26325518, 2015). "The ability of oxidised PTEN to regain its tumour suppressive activity depends on the capacity of thioredoxin to reduce the inactive form, and a total loss of PTEN function can occur if the redox status of the cell is abnormal." (PMID 16495927, 2006). "Strong expression of TXN and TXNIP in cytoplasm, at cell membrane and translocation into nuclei of EVT cells, associated precursor lesions as well as in ESRD/ACRD associated tumours suggest as the involvement of TXNIP/TXN signalling in the development of these unique type of tumours." (PMID 39020292, 2024). "Similarly, to GSH, changes to thioredoxin (Trx) metabolism are implicated in tumor cell resistance to chemotherapy." (PMID 29770165, 2018). "Increased thioredoxin expression has been seen in a variety of malignancies and recent evidence suggests that it may be associated with aggressive tumor growth and poor survival." (PMID 25871387, 2015). "The relevance of the thioredoxin system, comprising Trx1 and TrxR1, has been underscored in cancer chemotherapy due to their increased expression in different human cancer types, associated with augmented tumor growth, drug resistance, and unfavorable prognoses." (PMID 38001739, 2023). "We focused on TXNRD1 and GSR, the key mediators of the thioredoxin- and glutathione-dependent systems, and deleted these enzymes alone or in combination to study their roles in tumor initiation and early progression." (PMID 40334547, 2025). "As a tumor with a high protein synthesis and secretion load, MM relies on the thioredoxin (Trx) system to reduce endoplasmic reticulum stress and oxidative stress." (PMID 40308607, 2025). "Numerous studies have investigated the characteristics of these antioxidant systems in tumor cells, documenting the roles of both the glutathione and thioredoxin systems in conferring chemotherapy resistance." (PMID 40076706, 2025). "To further investigate the relationship between Trx system and tumor immunity, we obtained the mRNA expression level of TXN, TXNRD1 and TXNIP at single-cell level using 10 datasets from TISCH data." (PMID 39744566, 2025). "Overall, these data suggest that the GSH and TXN systems have different, although complementary, roles in initiation and progression and that inhibition of both systems impairs tumor formation and progression." (PMID 40334547, 2025). "This is due to the fact that components of the redox system, for example, GSH and thioredoxin, are involved in protecting tumor cells from apoptosis and in the formation of multidrug resistance." (PMID 38785550, 2024). "Recent preclinical studies have shown that inhibiting GSH or Thioredoxin (Trx) antioxidant systems, which are downstream of Nrf2 signalling, can sensitise various tumour cell types to cancer therapy." (PMID 39456749, 2024). "Based on this, one of the directions is associated with the development of drugs that block the synthesis of GSH and thioredoxin in tumor cells." (PMID 38785550, 2024).
tumor (continued). "The frequency, increased level and cellular localisation of TXNIP/TXN in tumours of ESRD/ACRD kidneys versus tumours of the general population suggests their role in ESRD/ACRD tumorigenesis." (PMID 39020292, 2024). "Nuclear expression of TXN was seen at less frequency in other types of tumours such as chRCC, pRCC and cRCC, which occurs not only in ESRD/ACRD kidneys but in the general population as well." (PMID 39020292, 2024). "In turn, ebselen—i.e., a synthetic organoselenoid molecule with anti-inflammatory, antioxidant and cytoprotective properties—has anti-cancer properties by inhibiting the activity of thioredoxin in tumor cells, inducing the apoptosis of tumor cells." (PMID 39457066, 2024). "Expression of TXNIP and TXN was examined in histological slides of 6 ESRD and 6 ACRD kidneys, precursor lesions and associated tumours as well as of RCCs from the general population by immunohistochemistry." (PMID 39020292, 2024). "TXN is a potent antioxidant that mediates many biological processes, including redox signaling and is closely related to tumor pathogenesis and therapy." (PMID 38902322, 2024). "TXN gene promotes hypoxia-inducible factor-1α, leading to vascular endothelial growth, tumor angiogenesis, and drug resistance." (PMID 37037466, 2023). "Harris reported that, with the growth of a tumor, thioredoxin (TxN) acts synergistically with GSH to buffer ROS levels, and the synthesis of TxN requires the export of glutamate in exchange for the import of cysteine." (PMID 37298317, 2023). "To determine the role of thioredoxin during tumor initiation, we generated a zebrafish thioredoxin mutant." (PMID 35250998, 2022). "Since the thioredoxin system is overexpressed in tumor cells, its inhibition appears as a promising therapeutic strategy to increase ROS levels and oxidative stress and induce GBM cell apoptosis." (PMID 35813817, 2022). "These mutants also exhibited enhanced neutrophil-dependent proliferation of transformed cells, suggesting that thioredoxin modulates neutrophil behavior and early tumor progression." (PMID 35250998, 2022). "For example, thioredoxin and thioredoxin reductase are crucial constituent parts of the thioredoxin system and are considered to be vital regulators of tumor development." (PMID 35884444, 2022). "Our findings indicate that thioredoxin suppresses the transformed cell growth through multiple mechanisms during tumor initiation in zebrafish larvae." (PMID 35250998, 2022). "Thioredoxin aids in dampening these ROS levels and thus can influence many signaling pathways in the tumor microenvironment." (PMID 35250998, 2022). "We developed a zebrafish thioredoxin mutant line to investigate the role of this antioxidant in the early tumor microenvironment." (PMID 35250998, 2022). "To characterize the role of thioredoxin during tumor initiation, we generated a thioredoxin (txn) mutant using CRISPR/Cas9 gene editing." (PMID 35250998, 2022). "Our findings suggest that thioredoxin is likely one of many factors that alters neutrophil behavior in the tumor microenvironment." (PMID 35250998, 2022). "Butaselen (BS), which was previously synthesized by our group, is an organic selenium compound that exerts antioxidant and tumor cell apoptosis–promoting effects by inhibiting the thioredoxin (Trx)/thioredoxin reductase (TrxR) system." (PMID 34540892, 2021). "This revealed a similar pattern in both populations with a decrease in hydrogen peroxide activity (downregulation of peroxiredoxin (PRDX) 1, 3, 4 and 6, and TXN) compared to non-tumor tissues." (PMID 33799792, 2021). "One of the well-documented mechanisms involved in tumor cell resistance to oxidative stress is the thioredoxin (Trx) system." (PMID 32219063, 2020).
tumor (continued). "Peroxiredoxin 2 is a redox regulatory protein that plays an important role in maintaining ROS homeostasis in the tumor microenvironment by coupling with the thioredoxin/thioredoxin reductase system." (PMID 32846884, 2020). "Although the role of thioredoxin system in the proliferation of tumoral cells and resistance to chemotherapeutic drugs has been found in some neoplasms, its role in oral SCC has remained unclear." (PMID 33289312, 2020). "Other small molecules like YC-1, thioredoxin inhibitors, 17-AAG, and 2ME2 were associated with the capacity of reducing the HIF-1α levels together with limitation of tumor growth and angiogenesis in vivo." (PMID 31817513, 2019). "Tumour cells upregulated and became dependent on the thioredoxin system, revealing a tumour vulnerability that can be efficiently targeted in a combination therapy approach." (PMID 31426306, 2019). "Thioredoxin was previously found to promote tumor growth through inhibition of apoptosis, reduce sensitivity of the tumor to drugs, and be associated with poor prognosis." (PMID 29482577, 2018). "This work revealed that glutathione and thioredoxin are required for tumour initiation, and that inhibition of these antioxidant systems hinders tumour growth in a synergistic manner." (PMID 29940987, 2018). "In tumor-bearing mice, a simultaneous disruption of the thioredoxin and glutathione systems by the combination of AF and buthionine sulfoximine was shown to significantly improve tumor radioresponse." (PMID 28415723, 2017). "Pre-NACT core needle biopsies and postoperative tumor samples were immunohistochemically stained for nuclear factor erythroid 2-related factor 2 (Nrf2), Kelch-like ECH-associated protein 1 (Keap1), thioredoxin (Trx), and peroxiredoxin I (Prx I)." (PMID 29348788, 2017). "The level of TrxR in tumor cells is often 10-fold or even greater than in normal tissues, and tumor proliferation seems to be crucially dependent on an active thioredoxin system." (PMID 25970775, 2015). "Recent studies have shown that TXN had high expression in many human primary tumor tissues such as the liver, colon, pancreas, and the uterine cervix." (PMID 26325518, 2015). "There was a significant correlation between thioredoxin concentrations and tumor size, Child-Pugh class or tumor stage (r = 0.311, P < 0.0001; r = 0.377, P < 0.001; r = 0.442, P < 0.0001; respectively)." (PMID 25871387, 2015). "Two of the major redox regulatory systems in mammals that support increased tumor growth are the thioredoxin (TXN) and the glutathione (GSH) systems." (PMID 26569310, 2015). "TXN increases proliferation and resistance to cell death, and promotes metastatic progression of tumor cells." (PMID 26325518, 2015). "TXNIP can reduce tumor invasion and angiogenesis through inhibition of thioredoxin and can directly impact cell survival by promoting a pro-apoptotic environment." (PMID 24645981, 2014). "TXNIP is a known binding partner and inhibitor of the cellular antioxidant and tumor promoter thioredoxin (Trx)." (PMID 24645981, 2014). "TXNIP is a negative regulator of cellular oxidative tolerance by binding thioredoxin and as a feedback regulator of S-nitrosylation relevant in the cellular adaptive response to tumor microenvironmental stresses." (PMID 20844768, 2010). "The tumor environment is usually under either oxidative or hypoxic stress and both stresses are known up-regulators of thioredoxin expression." (PMID 24281068, 2010). "Another PTEN-binding protein, thioredoxin, is a redox protein that is overexpressed in a large number of tumours." (PMID 16495927, 2006). "In tumor cells, the thioredoxin (Trx)/thioredoxin reductase (TrxR) couple produces a reduced form of extracellular Trx, which acts as a growth factor conferring protection from the NK-lysin, tumor necrosis factor-α and the T-lymphocyte respiratory burst." (PMID 16759382, 2006). "Thioredoxin as a molecular target is upstream of several regulatory processes key to the survival of tumours." (PMID 15655539, 2005).